EDDM3B (epididymal protein 3B)
Description:
Possible function in sperm maturation.
Synonyms: HE3-beta; FAM12B; HE3B; EP3B; RAM2
Tractability: Antibody: UniProt places it where antibodies can reach, with high confidence; UniProt predicts a signal peptide or a membrane-spanning region; its Gene Ontology location is reachable by antibodies, with medium confidence.
Gene: Protein-coding gene on chromosome 14 (20,768,404 to 20,770,948, forward strand). Ensembl gene ENSG00000181552.
Subcellular location: Secreted
Gene Ontology:
Molecular function: protein binding
Cellular component: extracellular region
Genetic constraint (gnomAD): Loss-of-function variants: 0 observed, 0.16 expected, observed/expected ratio (o/e) 0, 90% interval 0 to 1.88. That is too few expected variants to judge how well the gene tolerates losing a copy. Missense variants: 185 observed, 185.53 expected, observed/expected ratio (o/e) 1, 90% interval 0.88 to 1.13. Synonymous variants: 70 observed, 60.1 expected, observed/expected ratio (o/e) 1.16, 90% interval 0.96 to 1.42.
Homologues: Orthologues: chimpanzee EDDM3B (99% identical), macaque EDDM3B (95% identical), rabbit RAM1 (63% identical), rat Eddm3b (56% identical), rat LOC103693823 (56% identical), pig EDDM3B (55% identical), mouse Eddm3b (54% identical), dog EDDM3B (51% identical). Paralogues in human: EDDM3A (69% identical).
Diseases named in the same sentence as EDDM3B in open-access papers:
EDDM3B is named in the same sentence as 8 diseases in open-access papers, as found by Europe PMC text mining. Sharing a sentence is not in itself a finding about the gene and the disease. The quoted sentences say what the papers report.
Azoospermia (1 paper, 2025). Absence of any measurable level of sperm,whereby spermatozoa cannot be observed even after centrifugation of the semen pellet. "Additionally, EDDM3B and LYZL1 were linked to spermatogenic failure, EDDM3B and CCDC90B with azoospermia, and EDDM3B with oligoasthenoteratozoospermia." (PMID 40497989, 2025).
brain tumors (1 paper, 2023). "For the other identified candidate biomarkers (EDDM3B, LMOD1, GP2, SPINT3, CTRL, OXT) there is no specific literature linking them to gliomas or other brain tumors." (PMID 36959545, 2023).
glioma (1 paper, 2023). A benign or malignant brain and spinal cord tumor that arises from glial cells (astrocytes, oligodendrocytes, ependymal cells). "We identified 8 plasma proteins which were increased in gliomas vs. meningiomas (GFAP, NEFL, EDDM3B, PROK1, MMP3, CTRL, GP2, SPINT3) and 4 proteins which were decreased in gliomas vs. meningiomas (FABP4, ALDH3A1, IL-12B and OXT)." (PMID 36959545, 2023).
Sertoli Cell-Only Syndrome (1 paper, 2025). A type of male infertility in which no germ cells are visible in any of the biopsied SEMINIFEROUS TUBULES (type I) or in which germ cells are present in a minority of tubules (type II). "TP53I11 and EDDM3B were also associated with Sertoli cell-only syndrome and TEX101, EDDM3B, and PLCZ1 with varicocele." (PMID 40497989, 2025).
EDDM3B also shares sentences with these, for which no sentence is quoted: asthma (1 paper); meningioma (1); oligoasthenoteratozoospermia (1); varicocele (1).